ENSG00000286088 (novel protein)
Synonyms: FAM24B-CUZD1
Gene: Protein-coding gene on chromosome 10 (122,832,167 to 122,879,583, reverse strand). Ensembl gene ENSG00000286088.
Genetic constraint (gnomAD): Missense variants: 321 observed, 337.28 expected, observed/expected ratio (o/e) 0.95, 90% interval 0.87 to 1.04. Synonymous variants: 120 observed, 128.98 expected, observed/expected ratio (o/e) 0.93, 90% interval 0.8 to 1.08.